INS (insulin)
Diseases named in the same sentence as INS in open-access papers (continued):
Sharing a sentence is not in itself a finding about the gene and the disease.
Insulin resistance (continued). "Nonetheless, insulin resistance, which compromises the insulin signaling pathway and impairs cardiovascular system performance, is common in individuals with T2DM." (PMID 40747301, 2025). "Ceramide lipids, a known lipotoxic molecule among sphingolipids, can interfere with insulin signaling pathways and exacerbate hepatic and systemic insulin resistance, which is one of the primary drivers of non-alcoholic fatty liver disease (NAFLD)." (PMID 41008164, 2025). "We have previously reported that 12-weeek T2DM rats exhibit reduced insulin sensitivity/insulin resistance." (PMID 40078371, 2025). "Experimental studies have shown that circadian misalignment decreases leptin, increases glucose despite higher insulin levels, and inverts the cortisol rhythm, promoting insulin resistance and metabolic dysfunction." (PMID 39856244, 2025). "Women with PCOS often exhibit localized insulin resistance, particularly in the endometrium, where key molecules in the insulin signaling pathway are impaired, leading to disrupted signaling and reduced glucose uptake." (PMID 40403007, 2025). "Previous preclinical studies have already demonstrated that EAAs act through the mTOR-mediated pathway on reducing insulin resistance through insulin-independent intracellular glucose transport." (PMID 40806660, 2025). "SOCS proteins, especially SOCS1 and SOCS3, negatively affect insulin signaling, linking cytokine signaling to insulin resistance." (PMID 40141412, 2025). "IL-1β is implicated in pancreatic β-cell damage, while TNF-α induces peripheral insulin resistance by altering insulin signaling through serine phosphorylation with the consequent development of T2DM." (PMID 41009326, 2025). "HBOT seems to improve glycaemic levels and insulin sensitivity, thus presenting a potential treatment approach to treat insulin resistance and its consequences." (PMID 41322229, 2025). "Free fatty acids accumulating in the body through lipotoxicity reduce beta-cell function by generating problems with insulin granule release and raising both mitochondrial stress and inflammation levels, which drive insulin resistance." (PMID 40225541, 2025). "miR-33 plays various roles in metabolic syndrome (atherosclerosis, obesity, liver fibrosis, insulin resistance) by regulating fatty acid oxidation, insulin signaling and glucose metabolism pathways." (PMID 40560451, 2025). "Leptin, another adipokine, is thought to contribute to the pathogenesis of PCOS by stimulating insulin secretion from adipose tissue, thereby exacerbating insulin resistance." (PMID 40149685, 2025). "Insulin resistance is a metabolic condition in which normal or elevated insulin levels fail to elicit the expected biological response, particularly in glucose metabolism." (PMID 40641901, 2025). "Insulin resistance, also referred to as impaired insulin sensitivity, occurs when liver, muscle, and adipose cells exhibit poor responsiveness to insulin and encounter difficulties in assimilating glucose from the bloodstream to produce energy." (PMID 40775340, 2025). "Insulin resistance, characterized by reduced responsiveness to insulin, can interfere with the normal signaling pathways of various hormones, including leptin." (PMID 40087612, 2025). "Insulin resistance, characterised by a reduced response of insulin‐targeting tissues, is a key driver of many metabolic diseases, such as type 2 diabetes, atherosclerotic diseases, and metabolic dysfunction‐associated steatotic liver disease." (PMID 40413611, 2025). "Several indices are used to provide insight into insulin resistance, insulin sensitivity, and β-cell function using fasting glucose, fasting insulin, lipids, and anthropometric measures." (PMID 40564223, 2025). "Earlier, it was shown that in a manner resembling insulin naringin regulates lipoprotein production and insulin sensitivity in mice with diet-induced insulin resistance in vivo." (PMID 40161891, 2025).
Insulin resistance (continued). "Serum prolactin, BMI, complete glucose-insulin profile and insulin resistance indices following OGTT were determined." (PMID 40362476, 2025). "The transient increased DAG content temporally caused insulin resistance by increasing protein kinase C-θ (PKC-θ) activation and inhibiting insulin-stimulated IRS-1 tyrosine phosphorylation and AKT2 phosphorylation." (PMID 41009753, 2025). "Mechanistically, insulin resistance promotes hepatic uptake of FFAs, impairs hepatic insulin signaling, and disrupts lipid metabolism, thereby accelerating hepatic fat accumulation." (PMID 40640543, 2025). "Insulin resistance (IR), defined as impaired insulin action in major target tissues such as muscle, adipose tissue, and liver, affects approximately 30% to 35% of PCOS patients, particularly those who are obese." (PMID 40547527, 2025). "Studies have demonstrated that mice fed a high‐fat diet exhibit increased NE activity, which induces cellular insulin resistance, while NE deletion in obese mice results in reduced inflammation of insulin‐sensitive tissues." (PMID 41340462, 2025). "Elevated fasting insulin is a key indicator of insulin resistance, a condition in which cells become less responsive to insulin." (PMID 40002771, 2025). "Insulin resistance disrupts not only lipid synthesis but also key insulin signaling pathways, such as protein kinase B (AKT) phosphorylation." (PMID 40243565, 2025). "BCFAs as one of the metabolism productions of BCAAs are likely to link with insulin resistance, and SCFAs from the fermentation of resistant dietary carbohydrates are known modulators of insulin secretion." (PMID 40078932, 2025). "Obesity is a metabolic disease that induces insulin resistance by altering the insulin signaling pathway through a mild inflammatory state." (PMID 40153388, 2025). "Even in the presence of significant insulin resistance, functional β-cells can produce sufficient insulin to counteract impaired insulin action." (PMID 40004800, 2025). "Insulin resistance (IR) is defined as the inability of insulin to implement glucose uptake and utilization by peripheral organs, mainly muscles, the liver, and adipose tissue, resulting in hyperglycemia and hyperinsulinemia." (PMID 40217851, 2025). "T2D cases can range from those with a phenotype with insulin resistance but having some functioning pancreatic beta cells to a phenotype that requires early insulin therapy." (PMID 39859066, 2025). "Elevated FFAs in circulation are a major driver of insulin resistance, disrupting insulin signaling pathways within ECs and exacerbating endothelial dysfunction." (PMID 40429748, 2025). "In the context of insulin resistance, β-cells undergo compensatory proliferation and secrete excessive insulin, eventually leading to increased endoplasmic reticulum stress and oxidative stress." (PMID 41488105, 2025). "Some studies have documented elevated fasting insulin levels and increased insulin resistance in patients with ISS receiving rhGH." (PMID 41347128, 2025). "Mechanistic work in insulin-resistant human kidney cells in vitro illustrates an association between renal ECM remodelling and insulin resistance." (PMID 41301516, 2025). "Sterol regulatory element-binding transcription factor 1, involved in insulin resistance and insulin signaling, was elevated." (PMID 40438215, 2025). "This condition arises from a defect in insulin secretion, a defect in insulin action (insulin resistance), or most commonly, a combination of these two pathophysiological disturbances." (PMID 41199866, 2025). "Specifically, for obese or overweight T2DM patients experiencing insulin resistance due to overnutrition, the efficacy of insulin therapy on endothelial function is likely influenced by the level of metabolic control achieved by these individuals." (PMID 40093018, 2025).
Insulin resistance (continued). "Insulin resistance can increase circulating glucose levels, a phenomenon that leads to a compensatory increase in insulin production in pancreatic β-cells, which in turn leads to hyperinsulinemia and a vicious cycle that further increases insulin resistance." (PMID 40583967, 2025). "Ectopic lipid accumulation resulting from obesity significantly diminishes insulin sensitivity, with over 80% of obese patients experiencing insulin resistance at some stage." (PMID 40076460, 2025). "Adipose tissue-specific AhR activation exacerbated insulin resistance, whereas adipose tissue-specific AhR deletion improved insulin sensitivity." (PMID 39941095, 2025). "SGLT2i reduced insulin resistance, as evidenced by decreased homeostatic model assessment for insulin resistance and insulin and fasting plasma glucose levels." (PMID 40485656, 2025). "The remaining five clusters were characterised by features of insulin resistance, highlighting the heterogeneity in the ways tissues fail to respond to insulin." (PMID 40741412, 2025). "No changes in MGU were observed in obese swine and adults with T2D, highlighting the importance of defective insulin signalling in myocardial insulin resistance and T2D6." (PMID 40593987, 2025). "This latter aspect promotes the development of insulin resistance and a subsequent decrease in receptor signaling, leading to increased glucose accumulation, which in turn supports further insulin secretion." (PMID 40868096, 2025). "High insulin level can be a consequence of insulin resistance but it can also be an independent primary defect indicative of an unfavourable metabolic health." (PMID 40273152, 2025). "Elevated cytokine levels inhibit insulin signaling, leading to the development of insulin resistance and increased infiltration of adipose tissue with macrophages." (PMID 40469441, 2025). "T2DM is marked by insulin resistance, manifesting as reduced insulin sensitivity that impairs glucose uptake and utilization, ultimately leading to hyperglycemia." (PMID 40729002, 2025). "While information regarding the effects of PA on brain insulin resistance has been provided mostly from studies of hypothalamic neurons, the analyses of other neuronal cell models have also shown that insulin signaling is blunted by PA." (PMID 40208460, 2025). "Disruptions in insulin signaling to lysosomes can impair lysosomal activity, contributing to the development of insulin resistance in podocyte." (PMID 39996055, 2025). "Insulin levels have been found to be a stronger metric than glucose levels for early identification of T2DM due to the tendency of insulin resistance to precede elevated glucose levels." (PMID 40428172, 2025). "Improvements were also seen in aggression, anxiety, and compulsivity, and there were reductions in leptin, insulin, and insulin resistance, as well as a significant increase in adiponectin." (PMID 40136445, 2025). "Concurrently, these groups displayed hyperglycemia, glucose intolerance, and insulin resistance, accompanied by decreased serum insulin concentration." (PMID 39808380, 2025). "Insulin resistance is another key factor in CKM Syndrome, associated with the disruption of insulin signaling by lipids and inflammation." (PMID 40376312, 2025). "Insulin resistance (IR) is due to the disruption of multiple molecular pathways, leading to decreased insulin sensitivity." (PMID 39933012, 2025). "This review aims to elucidate how mitochondrial bioenergetics and oxidative stress collectively contribute to insulin resistance in insulin-sensitive tissues." (PMID 41480360, 2025). "Activating α-glucosidase activity, promoting glycogen synthesis, alleviating insulin resistance, and enhancing the body’s sensitivity to insulin as well as glucose transport capacity." (PMID 41189619, 2025). "It is almost always related to insulin resistance in peripheral tissue and impaired insulin secretion due to β-cell failure." (PMID 41179869, 2025).
Insulin resistance (continued). "Administration of γ-PGA in diabetic mice resulted in improved lipid metabolism, insulin resistance, HOMA-IR, reduced FBG, and enhanced expression of genes associated with the insulin pathway: INSR, Akt, IRS-1, and PI3K." (PMID 40573100, 2025). "Diets rich in carbohydrates with a high glycemic index, which causes rapid spikes in blood glucose and insulin levels, can promote DNL and contribute to hepatic steatosis and insulin resistance over time." (PMID 40647314, 2025). "In individuals with DM, insulin resistance is characterized by reduced insulin sensitivity, leading to impaired glucose uptake and utilization, which ultimately contribute to hyperglycemia." (PMID 40729002, 2025). "When comparing clinical, hormonal, and biochemical values, the median levels of TSH, anti-TPO, anti-Tg, glucose, triglycerides, insulin, and homeostatic model assessment for insulin resistance score were significantly higher in the HT group (p < 0.05 for all)." (PMID 40337564, 2025). "Normal-weight patients with a lipodystrophy-like phenotype are also strongly characterized by insulin resistance and impaired secretion of insulin." (PMID 39940862, 2025). "Clinically, insulin resistance is defined by a requirement for excessive insulin to mediate the appropriate response to a glucose load, or higher-than-expected blood glucose levels relative to insulin." (PMID 40013621, 2025). "Insulin resistance, a condition where the body’s cells become less responsive to insulin, leads to higher circulating insulin levels." (PMID 40933557, 2025). "Decreased adiponectin levels reduce insulin sensitivity, while increased leptin levels, combined with leptin resistance, fail to counteract insulin resistance effectively." (PMID 39857741, 2025). "Among insulin-based methods, the homeostasis model assessment of insulin resistance (HOMA-IR) is the most widely used and validated surrogate index, calculated from fasting glucose and insulin concentrations." (PMID 40843744, 2025). "The DNA methyltransferase DNMT3A mediates adipose insulin resistance through its downstream target gene Fgf21, a gene known to enhance glucose uptake and insulin sensitivity." (PMID 40862085, 2025). "Recent research has indicated that the gut microbiome potentially influences intestinal carbohydrate metabolism and improves insulin resistance, suggesting that intestinal carbohydrate metabolism plays an important role in insulin sensitivity." (PMID 41394123, 2025). "Those with MASLD manifest features of insulin resistance including higher mean BMI and greater insulin dose requirements." (PMID 40568565, 2025). "It is characterized by insulin resistance, a condition in which the body’s cells fail to respond effectively to insulin, prompting the pancreas to produce increasing amounts of insulin to maintain euglycemia." (PMID 41311837, 2025). "Insulin resistance, characterized by the diminished responsiveness of cells to the glucose-lowering effects of insulin, is also prevalent in RA." (PMID 40218212, 2025). "Broadly speaking, there are two subclasses of DM that have been characterized by either the inability of the body to produce insulin (Type 1) or the progressive development of insulin resistance in tissues (Type 2)." (PMID 40429969, 2025). "Insulin resistance exacerbates muscle degradation via dysregulation of insulin and insulin-like growth factor 1 signaling." (PMID 40717956, 2025). "The research revealed that oleate alleviated palmitate-induced insulin resistance by modulating inflammatory pathways associated with ROS and the JUN-encoded protein, a key inflammatory mediator that disrupts insulin signaling." (PMID 39940428, 2025). "A prior study demonstrated that the physiological and affective characteristics of long COVID are linked to higher levels of fasting blood glucose and insulin, as well as an elevated HOMA2IR index, suggesting the development of insulin resistance." (PMID 40048451, 2025).
Insulin resistance (continued). "Insulin and HOMA-IR levels were significantly higher in the obese group compared to the control group, indicating insulin resistance associated with obesity." (PMID 40283014, 2025). "In support of these mechanisms, experimental data have demonstrated that Pb exposure disrupts insulin secretion and upregulates hepatic gluconeogenic enzymes, leading to hyperglycemia and insulin resistance." (PMID 41009549, 2025). "In the early stages of T2D pathogenesis, the body produces insulin, but its ability to reduce blood glucose levels is inadequate (insulin resistance)." (PMID 40662943, 2025). "Mechanistically, SGLT2 blockade reduces renal glucose reuptake, induces glycosuria, and lowers plasma glucose levels through an insulin-independent mechanism, an important advantage in patients with impaired β-cell function or insulin resistance." (PMID 41157306, 2025). "This is the first study that evaluates insulin clearance and hepatic insulin resistance in the context of obesity and OSA in paediatric age." (PMID 40365648, 2025). "When insulin resistance is present, normally functioning pancreatic beta cells increase the secretion of insulin to maintain blood glucose levels." (PMID 39422718, 2025). "Origanum majorana can reduce insulin levels and the homeostasis model insulin resistance index, improve insulin sensitivity in women with polycystic ovary syndrome." (PMID 40842497, 2025). "Insulin resistance (IR) elevates insulin levels, activating pathways that promote aggressive breast cancer biology." (PMID 41195424, 2025). "Variations in this concentration can lead to peripheral insulin resistance by disrupting the insulin signaling cascade and reducing glucose transporter activity." (PMID 41019331, 2025). "Insulin resistance is a metabolic condition in which the insulin-sensitive tissues (skeletal muscle, liver, adipose tissue) become less responsive to insulin action." (PMID 41585812, 2025). "T2D emerges when pancreatic β‐cells are unable to secrete sufficient insulin to overcome peripheral insulin resistance." (PMID 40270326, 2025). "With effects that differ greatly depending on physiological conditions and insulin resistance, insulin plays a crucial role in the cardiovascular system through both direct and indirect mechanisms." (PMID 41007785, 2025). "Preclinical and clinical studies have demonstrated that ghrelin contributes to poor glycemic control by suppressing insulin secretion and promoting hyperglycemia and insulin resistance." (PMID 41416093, 2025). "In clinical practice, the Homeostasis Model Assessment of Insulin Resistance (HOMA-IR) is commonly used to evaluate insulin sensitivity." (PMID 41446289, 2025). "VDD increases insulin resistance, decreases insulin sensitivity, and impairs beta-cell function by affecting the molecular repair mechanisms of these cells." (PMID 40313432, 2025). "The risk of MetS was evaluated using the continuous metabolic syndrome score (cMetS), and insulin resistance was assessed using fasting blood insulin and homeostasis model assessment of insulin resistance (HOMA-IR)." (PMID 39756373, 2025). "High levels of Fe increased the burden on the liver, reduced the sensitivity of the liver to insulin, induced insulin resistance, reduced the synthesis of liver glycogen and weakened the sensitivity to insulin signals." (PMID 40612310, 2025). "Compensatory increases in insulin secretion follow, ultimately resulting in systemic insulin resistance." (PMID 41357227, 2025). "T1D is an autoimmune disease resulting from impaired insulin secretion, while T2D is mainly due to insulin resistance and dysfunction of pancreatic β-cells." (PMID 40260393, 2025). "This confidence stems from our methodological approach of collecting cells from individuals with confirmed insulin resistance and insulin sensitivity, which provides a strong foundation for our findings and conclusions." (PMID 41574186, 2025).